CD4 (CD4 molecule)
Diseases named in the same sentence as CD4 in open-access papers (continued):
Sharing a sentence is not in itself a finding about the gene and the disease.
tetanus (70 papers, 2005 to 2025). A serious infectious disorder that follows wound contamination by the Gram-positive bacterium Clostridium tetani. "We aimed to determine if the number of Meningococcal (Men) C- and Y- specific memory B cells and; number and quality of Tetanus Toxoid (TT) carrier-specific memory CD4+ T cells are associated with polysaccharide-specific IgG post HibMenCY-TT vaccination." (PMID 26191794, 2015). "Better immunogenicity—particularly for diphtheria and tetanus—has also been linked to milder disease stage (CDC stage 1 or 2) and higher CD4+ levels at the time of the last vaccine dose." (PMID 40872956, 2025). "In wP-primed participants, the percentage of activated pertussis and tetanus antigen-specific CD4+ T cells was significantly increased post- vs pre-booster vaccination." (PMID 39149302, 2024). "In the presence of CF1D12, suppression by seminal fluid of CD4+ T-cell proliferation in PBMCs in response to tetanus was abolished." (PMID 39737172, 2024). "The proportion of antigen-specific CD4+ T cells was significantly different between C-peptide and tetanus toxoid (two-tailed t-test, p = 0.0095)." (PMID 39530093, 2024). "While the magnitude of responses detected in the CD4-deficient patients was above background, they were generally reduced two- to threefold compared with healthy donors (n = 9; 1.85% tetanus- and 4.5% Candida-specific CD4+ T cells)." (PMID 38557723, 2024). "The bystander activation of CD4+ T cells was reported in humans and a mouse model following booster vaccination with tetanus toxoid." (PMID 35418996, 2022). "These four peptides inhibited the expansion of Tetanus Toxoid-specific memory CD4+ T cells in a standardized Treg assay (the TTBSA), similar to other well-defined Treg epitope peptides." (PMID 34220802, 2021). "The recombinant tetanus vaccine shows strong immune responses (seroconversion rates, geometric mean titer, and antigen‐specific CD4+/CD8+ T‐cell responses), which are roughly comparable to those of the TT vaccine." (PMID 34081408, 2021). "In mice that had been preimmunized with tetanus, CD8 dependent immune responses, elicited with the oncolytic vaccine, were more effective when the used oAds were additionally loaded with a CD4-restricted tetanus peptide." (PMID 33202717, 2020). "A high-titer of Che a 2-specific IgG antibody was observed in mice immunized with the vaccine containing universal CD4+ T cell epitope from tetanus and diphtheria toxoid (Che a 2.rsT.D) compared with those immunized with rChe a 2 or Che a 2.rs." (PMID 32742602, 2020). "Tetanus Toxoid-specific CD4+ T-cell proliferation was maximal at 0.25 μM VPD450 and this concentration was selected to provide the best balance between staining intensity and CDI." (PMID 33424839, 2020). "The present study provided an antigen depot with the water-in-oil emulsion with IFA, TLR agonists to activate APC, and a tetanus peptide that is very effective at inducing CD4 helper T cell responses." (PMID 31248461, 2019). "In vivo application of GM-CSF lead to enhanced production of diphtheria-specific antibodies as well as more diphtheria-specific CD4+ T cells following vaccination with multivalent tetanus/diphtheria vaccine." (PMID 29961602, 2018). "The cytokine production of CD4+ T cells was studied by flow cytometry and cytokine-producing CD4+ T cells are referred to as diphtheria- or tetanus-specific CD4+ T cells." (PMID 29961602, 2018). "For co-cultures with memory CD4+ T cells we utilized memory responses induced by tetanus vaccination to mimic an antigen-specific stimulation." (PMID 30692988, 2018). "In cultures stimulated with CMV, EBV, influenza and tetanus peptides, the CD4+ T‐cell count correlated with IL‐1β (P = 0.045) and CD8+ T‐cell count with IFNγ (P = 0.013) and IL‐1β (P = 0.012)." (PMID 30323928, 2018).
tetanus (continued). "On the contrary, TT DNA immunization induced tetanus-specific CD4+ T cells with a Th1-dominated phenotype most likely imprinting the Th1 phenotype to Env-specific B cells during the VLP booster immunizations." (PMID 29743369, 2018). "Either eTACs or cDCs were pre-loaded with tetanus toxoid before the addition of autologous memory CD4+ T cells, containing vaccine-induced tetanus-specific memory responses." (PMID 30692988, 2018). "Bystander activation of CD4+ T cells is less well studied, but it was demonstrated that unrelated memory CD4+ T cells can be activated after a recall tetanus vaccination via bystander activation." (PMID 28489886, 2017). "Both patients presented with severely decreased numbers of naïve CD4+ T cells and defective T independent IgG responses to bacterial polysaccharide antigens, while T cell-dependent IgG antibody formation e.g. after tetanus or TBEV vaccination was intact." (PMID 26186701, 2015). "In individuals with advanced-stage HIV, the response is suboptimal for both tetanus and diphtheria, while in subjects with CD4 > 300 cells/μL, the response against tetanus is optimal, comparable to subjects without HIV while, for diphtheria, it can remain markedly lower." (PMID 37766251, 2023). "Results indicated that the only vaccine containing the universal CD4+ epitopes from tetanus and diphtheria toxoid, r.Che a 2.rsT.D, could significantly boost Che a 2–specific IgG response in aged mice." (PMID 32742602, 2020). "The frequency of IFN-γ-producing CD4+ T cells was significantly increased within PBMCs from vaccinated horses following stimulation with CuMVTT and the tetanus toxoid, whereas only for tetanus toxoid unvaccinated horses showed a significantly increased IFN-γ frequency." (PMID 32397549, 2020). "Also, the presence of pre-existing CD4+ cell memory to the mentioned TD epitopes in tetanus and diphtheria vaccinated individuals can induce a rapid and robust antibody response against the TD-epitope-fused allergen." (PMID 32742602, 2020). "The important aspect of our study is that responding CD4+ T cells to all vaccine antigens, including Tetanus and Pertussis, were significantly affected by the strain of immunizing BCG, with the Denmark strain inducing the highest magnitude of responses and a Th1 polyfunctional subset." (PMID 31649662, 2019). "Generic peptides, such as tetanus, have been used to boost CD4+ T cell activity systemically." (PMID 27576783, 2016). "Furthermore, characterization of tetanus-specific CD4 T cells in healthy human donors (identified using HLA tetramers bearing tetanus peptide), demonstrated the existence of this CXCR5+CXCR3−PD-1low phenotype among resting antigen-specific memory cells." (PMID 25699040, 2015). "No other factors showed a significant correlation with seroprotection, except for the CD4+ count and the viral load values at the time of the last dose of the primary vaccination series for mumps and the CDC3 stadium in 2023 for tetanus." (PMID 40872956, 2025). "The Tetanus Toxoid Bystander assay (TTBSA) was used to determine the effect of NSP7-289 on effector T cell suppression and TT-specific CD4+ T cell proliferation." (PMID 38124752, 2023). "In comparison, the authors found combination vaccines against diphtheria, tetanus and pertussis (DTaP vaccine) to be significant sources of possible cross-reactive immunity to SARS-CoV-2 spike protein, which included numerous CD4, CD8, and B cell epitopes." (PMID 36211404, 2022). "The Bifidobacteria-dominated microbiome signature sustainably improves immunological memory, i.e., CD4 responses to BCG and tetanus, tetanus-specific IgG and stool polio-specific immunoglobulin A at 2 years of age." (PMID 35922638, 2022). "Positive T‐cell responses among specific CD4 and CD8 T‐cells in participants receiving recombinant tetanus vaccine peaked at day 14 after booster vaccination and then declined gradually for the remainder of the study." (PMID 34081408, 2021).
tetanus (continued). "In this assay, THP-1-derived M1 macrophages internalize the extrinsically applied antigen Tetanus toxoid (TT) by endocytosis, and after processing of the antigen, present fragments on their MHC II receptor to human primary Tetanus toxoid-specific CD4+ T cells." (PMID 33940547, 2021). "Herein, we explore the role of CD4+FOXP3+CD127− Tregs in controlling immunity in infant males and females to vaccination with diphtheria–tetanus–whole cell pertussis (DTP) and/or measles vaccine (MV)." (PMID 28855899, 2017). "Tetanus Toxoid (TT) responses were tested in 2 individuals and TT specific cells (2.82% CD25+134+ of CD4+ T cells) had a distinctly different TF expression pattern." (PMID 24124462, 2013). "In the absence of seminal fluid, CF1D12 alone increased CD4+ T-cell proliferation in response to tetanus, which we attribute to blocking by CF1D12 of soluble CD52 released upon T-cell activation." (PMID 39737172, 2024). "Pertinent immunological studies reported low CD3 and CD4 counts; B cell testing demonstrated response to candida antigen but not tetanus antigen." (PMID 34938854, 2021). "Although CD4+ Th1 cytokine responses are not cognate correlates of protection against Tetanus and Pertussis, they are likely important measures of overall immune responsiveness to heterologous antigens." (PMID 31649662, 2019). "In our study, we compared CD4+ T cell immunity to BCG, Tetanus and Pertussis vaccines in two cohorts of newborn infants recruited from Jos, Nigeria and Khayelitsha, Cape Town, South Africa, and then interrogated the effects of BCG strain further in the Cape Town cohort." (PMID 31649662, 2019). "In doing this, we found a positive correlation between GM-CSF production by CD4+ T cells and diphtheria-, but not tetanus-specific antibodies." (PMID 29961602, 2018). "Therefore, we studied the TCR repertoire of CD4 and CD8 TNaive and TEM cells in 9-year old children receiving a combination vaccine against diphtheria, tetanus, acellular pertussis and inactivated poliovirus (DTaP-IPV)." (PMID 25923356, 2015). "Among the other categories of assessed HIV vaccine-induced immune responses (IgA-binding antibody responses, ADCC activity, and CD4+ T-cell responses), none of the correlations with tetanus-induced immune responses or with HBV-induced immune responses were significant." (PMID 39339842, 2024). "Multiple individual seminal fluid samples diluted out to 1:200 or more suppressed proliferation of CD4+ T cells in response to tetanus, determined by dilution of CFSE dye labelled PBMCs and suppression of IFN-γ production by PBMCs in response to tetanus, determined by ELISpot assay." (PMID 39737172, 2024). "One report described that tetanus-antigen-specific proliferation was induced in CD4+CD45RO+CXCR5−but not CD4+CD45RO+CXCR5+ cells, thus suggesting that Tfh cells likely disappear along with germinal centers, and are prone to apoptosis due to their high levels of Fas expression." (PMID 25699040, 2015).
kidney transplant (69 papers, 2011 to 2025). A surgical procedure in which one or both kidneys from a donor are implanted into a recipient. "Our study findings revealed a positive correlation between myeloid cells and susceptibility to prostatitis, while CD4 Treg %CD4, Activated & resting Treg % CD4+, and CD25hi %T cell in Treg cells were identified as suppressors of this risk." (PMID 39323879, 2024). "The maturation stages of T cells, specifically the expression of HVEM on CD4+ cells, were significantly associated with an elevated risk of prostatitis (OR = 1.2328, 95% CI = 1.0157 to 1.4963; p = 0.0341)." (PMID 39323879, 2024). "The glutamine degradant levels mediated the causal relationship between HLA DR+ CD4+ %T cells and prostatitis, with a mediation effect of −0.012, accounting for 8.07% of the total." (PMID 39465812, 2024). "The results in this study showed that the indirect effect of glutamine degradant levels in mediating the causal relationship between HLA–DR+CD4+ %T cells and prostatitis was −0.012, accounting for 8.07% of the total (P = .024 < 0.05)." (PMID 39465812, 2024). "As immune cells such as CD4 T cells migrate to lung tissue due to the lung inflammation caused by PM10D, the hematological analysis of white blood cells showed a reduced cell number following PM10D exposure." (PMID 39519565, 2024). "GC-resident CD4+ TFH cells in children with recurrent tonsillitis, caused by S. pyogenes infection, can become phenotypically skewed into pathogenic B cell killing effectors, which reduces humoral immunity as a consequence." (PMID 32858901, 2020). "Reduced CD4 count (hence severity of HIV infection) may be an important risk factor for chronic lung and heart disease." (PMID 25397462, 2014). "Therefore, we hypothesized that CD4+ T cells might change the risk of prostatitis, which might be mediated by the metabolic pathway of glutamine." (PMID 39465812, 2024). "To determine the contribution of CD4+ T cells in senescent recipient kidney transplant rejection, we also performed reclustering of CD4+ T cells, identifying five subclusters." (PMID 40234384, 2025). "Our study further demonstrated that M2 EVs directly acted on ILC2s and indirectly affected macrophages and CD4+ T cells, which in turn enhance the function of ILC2s, exacerbating lung inflammation." (PMID 40451928, 2025). "The analyses identified that particular T-cell subsets-notably CD3 + CD4 + T lymphocytes and CD3 + CD8 + T cells-demonstrated significant causal associations with elevated prostatitis risk." (PMID 40453586, 2025). "CD8+ and CD4+ tumors–infiltrating lymphocytes are associated with HPV status and clinical outcomes in tonsillar and base of tongue squamous cell carcinoma." (PMID 41181349, 2025). "This study aims to elucidate the precise contribution of different CD4+ memory T cell subsets to alloreactivity in highly sensitized (HS) kidney transplant recipients." (PMID 38993777, 2024). "Analysis between the groups of lip tumors according to the low and high presence of tumor budding showed a significant increase of CD4+ TILs in the invading front in the high TB group (p = 0.04)." (PMID 36900270, 2023). "CD4+ T-cell subsets promote liver autoimmune inflammation and regulate the progression of AIH through cytokine secretion and other mechanisms." (PMID 37695088, 2023). "Significantly higher RNA expression levels of CD4 are found in blood samples of patients with T-cell-mediated kidney transplant rejection." (PMID 36330810, 2022). "The first CAR-Treg clinical trial has been granted authorization in the UK and the Netherlands (STEADFAST) applying anti-HLA-A2 CD4 Tregs in kidney transplant patients (EUCTR2019-001730-34-NL)." (PMID 34575843, 2021). "Animal models, named as experimental autoimmune prostatitis, with the characteristic of CD4-positive T cell infiltrates, have been used as standard in vivo models to study the progress of prostatitis." (PMID 27564257, 2016).
kidney transplant (continued). "Together, both in vivo mouse assay and in vitro cell migration assay conclude that ASC-J9® can reduce the prostatitis via reduction of the CD4+ T cell migration to the prostate that involved the modulation of the CCL2 expression." (PMID 27564257, 2016). "In this study, we demonstrated that infiltrated CD4+ T cells play important roles in prostatitis by using NOD mice which can be rescued by ASC-J9®, the newly developed AR degradation enhancer." (PMID 27564257, 2016). "In this study, the effect of CP-690,550 on IL-2-mediated JAK/STAT5 phosphorylation by CD4+CD25brightFoxP3+CD127–/low regulatory T cells (Tregs) and CD4+CD25– effector T cells (Teffs) was examined in kidney transplant patients." (PMID 24565406, 2013). "The loss of the T memory response following TBI was associated with a relative increase of CD4+CD25+ Foxp3+ expressing T regs, as compared to the CD8+ T effector cells requisite for skin graft rejection." (PMID 22723935, 2012). "In the regulatory chain of “HLA–DR+CD4+ %T cells–Glutamine degradant levels–Prostatitis,” HLA–DR+CD4+ %T cells positively influence the metabolic pathway of glutamine (beta = 0.045 > 0), while this pathway negatively regulates the risk of prostatitis (beta = −0.267 < 0)." (PMID 39465812, 2024). "Children with RT caused by GAS infections display lower titres of antibodies against SpeA, compared to those with singular bouts of tonsillitis, and possess GC-resident CD4+ TFH cells that have become phenotypically skewed into pathogenic B cell killing effectors in the tonsil." (PMID 32858901, 2020). "In this study, we investigated whether CD161+CD4+ T cells can reflect the Th17 pathway in kidney transplant recipients (KTRs) and investigated the clinical significance of this cell type in chronic antibody-mediated rejection (cAMR) in KT." (PMID 30011312, 2018). "Next, we examined whether CD161+CD4+ T cells show clinical significance in kidney transplant recipients." (PMID 30011312, 2018). "As the percentage of CD25+FOXP3+ cells within the CD4+ subpopulation was reduced in kidney transplant patients, for the suppression assays a gate was set to sort Tregs containing >85% of CD4+CD25hiFOXP3+ T cells similar to the control group (CD4+CD25veryhi gate)." (PMID 28316600, 2017). "However, we found that the frequency of ST2L-expressing CD4+ cells was increased in liver granuloma (10 ± 2% of CD4+ cells vs 0.6 ± 0.1% in control livers) with no significant upregulation in the spleen (data not shown)." (PMID 27445267, 2016). "In addition, CD4+CD25bright Tregs from kidney transplant patients receiving CP-690,550 vigorously suppressed the proliferation of Teffs." (PMID 24565406, 2013). "The aim of this study was to determine whether the abundance of regulatory T cells (Tregs) (CD4+CD25high) affects the de novo development of anti-HLA donor-specific antibodies (DSAs) in kidney transplant recipients (KTRs)." (PMID 22970343, 2012). "Our immune profile analysis showed that, in our cohort of kidney transplant recipients, a higher amount of the circulating TR3-56 regulatory T cells preferentially associates with a decreased number and growth ability of the Treg, as well as with increased activation of the CD4+ T lymphocytes." (PMID 39408939, 2024). "In addition, LAIR-1 expression levels on CD3+, CD4+, and CD8+ T cells were all negatively associated with liver inflammation and fibrosis parameters, such as alanine aminotransferase and aspartate aminotransferase levels, FibroScan value, and aspartate aminotransferase-to-platelet ratio index score." (PMID 34398030, 2021). "Together, results from in vivo and in vitro studies suggest that ASC-J9® can suppress prostatitis by altering the autoimmune response induced by CD4+ T cell recruitment, and using ASC-J9® may help us to develop a potential new therapy to battle the prostatitis with little side effects." (PMID 27564257, 2016).